ALB (albumin)
Diseases named in the same sentence as ALB in open-access papers (continued):
Sharing a sentence is not in itself a finding about the gene and the disease.
tumor (continued). "In contrast, the HELPP score integrates not only laboratory markers (CRP, albumin, platelet count) but also tumor markers (CEA, CA19-9) and the ASA physical status score, thereby offering a broader assessment of both oncologic and clinical status." (PMID 41517561, 2025). "Its albumin-bound formulation facilitates uptake by both tumor and immune cells, with internalized albumin-bound paclitaxel exhibiting marked immunostimulatory activity, thereby promoting cancer immunity cycles." (PMID 41550955, 2025). "The two groups were compared in terms of age, preoperative nutritional intervention, BMI, smoking, drinking, TNM staging, tumor differentiation, intraoperative blood transfusion, albumin, hemoglobin, prealbumin, C-reactive protein, and WBC." (PMID 40589635, 2025). "In another study, gold nanorods were encased in albumin nanoparticles to exploit biocompatible albumin as a carrier to enhance tumor targetability and in vivo photothermal activity." (PMID 40084020, 2025). "Research indicates that albumin binds to the 60 kDa glycoprotein receptor (gp60, gene name albondin) located on vascular endothelial cells, facilitating its transport into the tumor interstitium through transcytosis." (PMID 41002483, 2025). "Increased mortality risk was associated with advanced age, lower albumin levels, reduced lymphocyte counts, decreased PNI, elevated neutrophil counts, higher NLR, increased HE4, H-NPS, and postoperative tumor residue." (PMID 40134604, 2025). "ROC analysis showed that the AUC of the nomogram was 0.738.Similarly, albumin level and tumor stage were also predictors of PPOI in our study." (PMID 40271430, 2025). "Last, tumor-draining lymph nodes are initiative sites for immune stimulation and lymphatic targeting via albumin-hitchhiking is receiving increasing attention." (PMID 41142425, 2025). "The albumin nanoparticles effectively inhibited tumor growth and prevented the development of metastasis in a mouse model, offering a promising approach for tackling both primary tumors and metastatic disease." (PMID 40343307, 2025). "The final model retained log‐transformed CA 19‐9, CEA, NLR and γ‐GT together with albumin, tumor size and lesion multiplicity." (PMID 41331584, 2025). "The GRIm score derives its efficacy from three pivotal biomarkers: LDH, NLR, and albumin, each contributing uniquely to tumor progression and patient prognosis." (PMID 41179670, 2025). "The therapeutic efficacy of albumin-CuET was evaluated in a syngeneic ectopic CT-26 CRC cold tumor model in BALB/c mice." (PMID 40013140, 2025). "TM4SF5 mRNA levels in tumor samples of TCGA–LIHC dataset were positively correlated with hepatic ALB levels." (PMID 40186033, 2025). "Albumin-bound paclitaxel is a broad-spectrum anti-tumor chemotherapeutic agent that is conjugated with human albumin and paclitaxel." (PMID 40980366, 2025). "Our results are coherent with previous report, where the conversion of crystalline lapatinib into amorphous form enhanced the solubility when encapsulated into poly(lactic-co-glycolic acid) (PLGA NPs) coated with albumin for tumor targeting." (PMID 40908968, 2025). "In parallel, easily available serum biomarkers of systemic inflammation and nutritional status, albumin, neutrophil-to-lymphocyte ratio (NLR), and lactate dehydrogenase (LDH), have repeatedly been linked to ICI outcomes in other tumour types." (PMID 41463022, 2025). "In the univariate analysis, there were marked differences in Group 2 (proximal), location, tumor size, HB, PT, and albumin(P < 0.05)." (PMID 40956808, 2025). "Collectively, our findings strongly suggested that ALB+KRT7+ EPCs originated organoids promoted tumour growth via Wnt/β‐catenin signalling." (PMID 39834100, 2025). "In this report, novel albumin-targetedplatinum(IV)-maleimide prodrugs based on picoplatin demonstrated enhancedplasma stability and tumor accumulation in mice." (PMID 39878587, 2025).
tumor (continued). "ROC analysis indicated high predictive value of the model for CSS when including age, SII, serum albumin level and platelet count, suggesting that immune response to the tumour and systemic inflammation are crucial in CRC patient survival." (PMID 40045061, 2025). "The negative impact of elevated SF was also evident in relation to the following variables: G-stage (P = < 0.001), T-stage (P = < 0.001), preoperative albumin levels (P = 0.013), tumor size (P = < 0.001), and CA 19 − 9 levels (P = < 0.001)." (PMID 40397178, 2025). "By incorporating both LDH, a surrogate marker of tumor metabolic activity, and albumin, which reflects systemic nutritional status, the LAR provides a comprehensive snapshot of the patient's physiological and oncological state." (PMID 40693202, 2025). "In a dorsal skin fold window chamber model, fluorescent dextran of similar radius to fluorescent albumin, the surrogate drug in this study, exhibited shallower tumor penetration than dextran of similar radius to iodixanol following intravenous administration." (PMID 41425223, 2025). "In ICC patients, ALB levels are often reduced due to tumor-related consumption and impaired liver function, which affects the normal metabolism and function of cells and thereby weakens the body’s ability to surveil tumor cells." (PMID 41256327, 2025). "CD spectrum of C/M@Alb NCs displayed the attributed peaks at 222 and 208 nm corresponding to albumin α-helical structure, indicating that the preserved structure of albumin in C/M@Alb NCs is promising for in vivo tumor targeting." (PMID 40908968, 2025). "Although albumin binders havebeen successfully applied to increasethe integral tumor uptake, the particular mechanisms that lead tothis increase are poorly understood." (PMID 40393943, 2025). "This process was initially proposed as a tumor-targeting mechanism, as many cancers exhibit increased albumin uptake." (PMID 41373734, 2025). "During tumor progression, elevated neutrophil levels and increased tumor burden lead to a reduction in albumin levels in the body." (PMID 41187199, 2025). "Serum albumin (ALB) functions not only as a key indicator of nutritional status but also modulates the tumor microenvironment through its anti-inflammatory and immunoregulatory effects." (PMID 41561745, 2025). "Human serum albumin significantly improves the solubility, stability and tumor targeting ability of poorly water-soluble photosensitizers by utilising multiple ligand-binding domains and EPR-independent tumor targeting." (PMID 41471095, 2025). "Low skeletal muscle promotes host systemic inflammation, characterized by a high neutrophil‐to‐lymphocyte ratio and low albumin levels, stimulating tumor cell proliferation and metastasis, worsening survival." (PMID 40385349, 2025). "A high tumor burden leads to significant albumin consumption, and such patients typically have poorer overall health, lower immune function, and reduced tolerance to chemotherapeutic drugs, making them more susceptible to myelosuppression." (PMID 39895779, 2025). "Based on the multivariate analysis, albumin level or LDH (clinical or tumor status) and LMR (immune status) were selected to develop models." (PMID 40579886, 2025). "ALB is related to the patient's nutritional status, tumor cells' generation of inflammatory cytokines, and liver function reserve." (PMID 40097940, 2025). "Albumin-modified gold NP (Alb-GNP) demonstrated effective accumulation in tumor cells, and their combination with radiotherapy produced a notably enhanced radiosensitizing effect and increased anti-tumor activity favorable for lung cancer decline." (PMID 40124344, 2025). "Targeting SPARC proteins in the tumor microenvironment using albumin to reduce allergic reactions and increase intra‐tumor drug concentrations." (PMID 40135802, 2025). "AJCC/UICC stage, serum albumin level, CapeOX treatment, tumor stage, and BMI were identified as significant independent prognostic factors for OS." (PMID 40571773, 2025).
tumor (continued). "We analysed the correlations between tumour volume and haematological indicators (β2-microglobulin, M-protein, free light chain, albumin, lactate dehydrogenase) and the trends after treatment intervention." (PMID 40777162, 2025). "This is particularly important for drug-delivery systems that bind to endogenous albumin in vivo, exploiting the ability of the protein to accumulate in tumor tissue." (PMID 40672673, 2025). "Regarding targeted therapy, the co-delivery of GEM and cetuximab via magnetic-albumin NPs permits not only the triple therapy by magnetic-targeted thermo-chemotherapy but also the targeting of both stromal and tumor cells." (PMID 40801679, 2025). "Overall, albumin plays a crucial role in transporting HMCDs, facilitating their accumulation for tumor imaging and targeted drug delivery." (PMID 39904854, 2025). "All 4 models identified albumin levels, transfer, and neoplasms as key predictors, although the magnitude of their impact varied across the models." (PMID 41343780, 2025). "Multivariate analyses identified AFP, ALB, tumor diameter, PVTT, TACE, and adjuvant therapy as independent predictors of OS, while AFP, multiple tumors, MVI, PVTT, TACE, and adjuvant therapy were associated with DFS." (PMID 41200181, 2025). "Given its abundant presence in blood (40 mg/ml) versus the interstitial fluid (14 mg/ml), serum albumin is transported into tumor tissues via diffusion-mediated flow through leaky vasculature." (PMID 41142425, 2025). "Compared to the control group treated with PBS containing 1% human serum albumin intravenously and liposomes intramuscularly, both combined therapy and NK cell therapy alone resulted in significant tumor growth inhibition." (PMID 40458686, 2025). "Maleimides are crucial in drug developmentdue to their abilityto react specifically with thiol groups, allowing precise conjugationto proteins (e.g., ADCs) and enhanced tumor accumulation via bindingto endogenous serum albumin." (PMID 39959040, 2025). "Important predictors across all models included serum albumin, tumor stage and size, extent of surgery, and intraoperative blood loss." (PMID 41462951, 2025). "ALB and APOH, frequently altered in HCC, contribute to metabolic reprogramming, a hallmark of tumor progression." (PMID 40307890, 2025). "Still, it is challenging to employ this strategy for organic small drug molecules such as MTX to be precipitated within albumin nanocavity and further developed drug-loaded albumin NPs with active tumor targeting capability." (PMID 40908968, 2025). "For this purpose, we sought to assess the tumor uptake of the free,i.e., albumin-unbound, and albumin-bound fraction and designed twonovel compounds accordingly." (PMID 40393943, 2025). "Independent predictors, including PG-SGA score, albumin level, hemoglobin level, previous abdominal surgery, operation time and advanced tumor stage (III-IV), were identified." (PMID 40271430, 2025). "Similar results have been observed by other research groups, with albumin-bound ligands exhibiting higher tumor accumulation and stronger retention." (PMID 40806707, 2025). "In multivariate analysis at both time points, BMD remained an independent predictor of survival, alongside tumor growth pattern, therapy, and Albumin-Bilirubin (ALBI) grade (alpha-fetoprotein reached significance only at time of PVTT diagnosis)." (PMID 40845067, 2025). "Isolating tdEVs using a microfluidic chip‐based protocol facilitated the removal of contaminants such as albumin and immunoglobulins and provided important high‐purity tumour proteomic information." (PMID 40545963, 2025). "Immunofluorescence indicated that TBP3743 tumors express mouse fibroblast activation protein (FAP), and prior work suggests favorable tumor-to-background albumin uptake over 48 h." (PMID 39753366, 2025).
tumor (continued). "Radioligands containing ALB can form high-molecular-weight complexes with albumin (∼66 kDa) in blood and show prolonged clearance from the kidney, resulting in increased tumor delivery and low renal uptake." (PMID 40308720, 2025). "The multivariate analysis identified several independent predictive factors for OS, including PLT, AST, ALB, tumor number, metastasis, and PD-1 inhibitor treatment (HR=0.63; 95% CI: 0.45-0.87, P =0.005)." (PMID 40574845, 2025). "Pre-operative variables (drawn ≤ 14 days before surgery) comprised CA19-9, CEA, AFP, CA-125, neutrophil-to-lymphocyte ratio (NLR), γ-glutamyl-transferase (γ-GT), albumin, maximum tumor diameter, and lesion multiplicity." (PMID 41331584, 2025). "The ASAR scoring system is based on albumin-bilirubin grade, tumor size, alpha-fetoprotein, and first TACE response." (PMID 39758864, 2025). "Here, four PDAC patient-derived xenografts (PDAC-PDXs) with different responses to gemcitabine plus nab-paclitaxel (nanoparticle albumin-bound paclitaxel) were studied to dissect the contribution of both tumor and host microenvironment to treatment response." (PMID 39902502, 2025). "LASSO–Cox regression identified age, clinical stage, tumor size, and albumin level as independent prognostic factors for OS." (PMID 41208979, 2025). "Continued development of this molecule, including the addition of an albumin moiety and the use of 64Cu as the imaging radionuclide have further improved tumor uptake and tracer circulation time, resulting in improved tumor visualization." (PMID 40863874, 2025). "Albumin protein acts as a tumor suppressor and plays a key role in HCC progression, particularly in tumor invasion and metastasis." (PMID 40941632, 2025). "Ferritin PROTACs spontaneously form tumor-targeting albumin nanoparticles via oleic acid binding, demonstrating potent MCL-1 degradation and enabling NIR-II image-guided surgery." (PMID 40871058, 2025). "The univariate analysis revealed that SII (p = 0.012), PIV (p = 0.003), albumin (p = 0.009), and tumor size (p = 0.036) were significantly predictive of LRFS." (PMID 39851955, 2025). "LASSO cross‐validation retained seven predictors including log‐transformed CA 19‐9, CEA, NLR and γ‐GT, serum albumin, maximal tumor diameter and lesion multiplicity." (PMID 41331584, 2025). "In the univariate analysis, several variables were predictive of overall survival (OS), including NLR, PLR, MLR, SII, PIV, CRP, LDH, albumin, tumor size, and Eastern Cooperative Oncology Group Performance Status (ECOG PS)." (PMID 39851955, 2025). "Tumor cells internalize albumin via macropinocytosis and degrade it in lysosomes, releasing bound paclitaxel." (PMID 41373734, 2025). "This mechanistic profiling enables rational design of albumin nanovehicles with enhanced drug loading, controlled release kinetics, and improved tumor specificity." (PMID 40871588, 2025). "Nano drug delivery systems use nanoscale carriers (such as liposomes, polymers, albumin, etc.)to improve the stability of gemcitabine, prolong circulation time, and increase accumulation through targeted release at tumor sites." (PMID 41293424, 2025). "Increased levels of urine albumin are related to advanced tumor stages and higher tumor burden, which are significant factors for cancer-related death." (PMID 41301732, 2025). "Human serum albumin nanoparticles interact with proteins derived from the tumor, which are acidic and have higher cysteine content and show increased activity in many cancer cells." (PMID 39926108, 2025). "The ALDH2 rs671 genotype was significantly correlated with tumor recurrence (3 [11.5%] vs 16 [36.3%], P = .024) and serum albumin levels (4.1 ± 0.3, 4.3 ± 0.3, P = .029)." (PMID 40660548, 2025). "Albumin-based formulations (nanoparticles, drug conjugates) demonstrate particular promise in oncology by improving solubility and tumor accumulation." (PMID 40871588, 2025).
tumor (continued). "The use of small-molecule albumin binders to extend the circulation time of pharmaceuticals and maximize their tumor uptake has become an attractive strategy for the design of endoradiotherapeutic agents." (PMID 40806707, 2025). "Previous studies have demonstrated that factors such as patients’ age, tumor differentiation, tumor size, serum alkaline phosphatase, albumin level, and CA 19–9 can serve as independent predictors of PC prognosis." (PMID 41208979, 2025). "Western studies often focus on general clinical variables, such as body mass index, American Society of Anesthesiologists grade, and albumin level, with limited emphasis on tumour background." (PMID 41189483, 2025). "Univariate analysis identified several factors associated with OS, including BW changes before and after treatment, Child-Pugh scores ≥ 8, ALBI grades 2 or 3, AFP levels ≥ 500 ng/mL, presence of infiltrative lesions, tumor size, and albumin levels." (PMID 41411278, 2025). "The patient underwent three cycles of neoadjuvant chemo-immunotherapy (albumin-bound paclitaxel, cisplatin, and anlotinib), followed by preoperative tumor vascular embolization." (PMID 41573654, 2025). "Given the progression of the tumor, salvage chemotherapy was initiated, combining albumin with paclitaxel and attilizumab, in consultation with a multidisciplinary team (MDT)." (PMID 39792773, 2025). "Chemotherapy with albumin-bound paclitaxel (200mg/m2) and cisplatin (50 mg/m2) was started on January 11, 2023, to inhibit tumor proliferation." (PMID 41346603, 2025). "In a 2020 study, lipid–albumin nanoparticles engineered to release paclitaxel in response to FAPα demonstrated enhanced tumor penetration and robust tumor regression in a pancreatic cancer mouse model, with minimal systemic toxicity." (PMID 41441395, 2025). "The hook effect has also been described in assays detecting albumin and a wide range of tumor markers." (PMID 40397359, 2025). "Folate-conjugated nanosystems for tumor theranostics include those based on MNPs, IONPs, and serum albumin." (PMID 40871005, 2025). "Human serum albumin(HSA) is a clinically validated drugcarrierthat improves drug delivery to tumor tissues." (PMID 40526060, 2025). "This albumin-hijacking approach leverages tumor-specific esterase overexpression to create a powerful dichotomy: normal tissue protection coupled with potent intratumoral protein degradation." (PMID 40871058, 2025). "While AuNPs and magnetosome-based NPs is good in imaging and cellular targeting, albumin-based NPs demonstrate excellent tumor selectivity and therapeutic outcomes." (PMID 41048541, 2025). "Studies have confirmed that albumin functions as an antitumor factor, directly inhibiting tumor cell proliferation." (PMID 40264786, 2025). "A study conducted on in vitro experiments using human liver cancer HepG2 cells and in vivo experiments using H22 tumor-bearing mice utilized resveratrol (RV) loaded on HAS (human serum albumin) nanoparticles in combination with folic acid." (PMID 40572668, 2025). "The existing liposome carriers have the problem of insufficient stability, while albumin can improve drug enrichment efficiency through the SPARC-mediated tumor uptake mechanism." (PMID 40871588, 2025). "The purpose of this study is to determine the impact of serum albumin levels on overall survival (OS) and tumor invasion/metastasis in HCC patients with the same liver function (ALBI grade) at the time of diagnosis." (PMID 41008815, 2025). "Markers such as creatinine, B2M, and albumin are also reflective of disease severity and tumor–host interactions." (PMID 41010591, 2025). "Albumin has been extensively explored as nanocarriers for precise tumor targeting due to their extended blood circulation (~19 d) and heightened tumor accumulation ability." (PMID 40908968, 2025).